TNF (tumor necrosis factor)
Diseases named in the same sentence as TNF in open-access papers (continued):
Sharing a sentence is not in itself a finding about the gene and the disease.
inflammatory bowel disease (continued). "Ruminococcus gnavus group is related to an inflammatory bowel disease called Crohn’s disease, and it can secrete an inflammatory polysaccharide that stimulates dendritic cells to produce inflammatory factors such as TNFα." (PMID 38385646, 2024). "Conversely, TNF, a pro-inflammatory cytokine, plays a crucial protective role in acute inflammatory bowel disease within the GI tract." (PMID 39206201, 2024). "Further research is needed to identify potential blood-based biomarkers predictive of response to anti-TNF therapy in patients with inflammatory bowel disease." (PMID 37801628, 2024). "TNF-α is a proinflammatory cytokine that triggers inflammation and pain in conditions like AP, hepatitis, and inflammatory bowel disease." (PMID 38784040, 2024). "Following the discovery of the critical pathogenetic role of tumor necrosis factor-α (TNF-α) in inflammatory bowel disease (IBD), monoclonal anti-TNFα antibodies have been developed and successfully adopted in clinical practice." (PMID 39685651, 2024). "A loss of S100β+ glial cells or glial networks was linked previously to increased proinflammatory cytokine levels (e.g., IFN-γ and TNF-α) in patients with inflammatory bowel disease." (PMID 39207863, 2024). "IL-6, TNF-α, IL-1β, and IL-10 serve as pivotal pathological mediators in inflammatory bowel disease." (PMID 39187810, 2024). "As the number of inflammatory bowel disease patients increases, the use of anti-TNFα inhibitors is also expected to rise, likely leading to more encounters with adverse effects." (PMID 39618753, 2024). "Adalimumab (ADA) is an antitumor necrosis factor (TNF) agent that is used in the treatment of inflammatory bowel disease (IBD), which includes Crohn disease and ulcerative colitis (UC)." (PMID 39496006, 2024). "For instance, monoclonal antibodies against TNF-α, such as infliximab and adalimumab, have revolutionized the treatment of diseases like RA, psoriasis, and inflammatory bowel disease." (PMID 38251210, 2024). "The role of therapeutic drug monitoring with non-TNF advanced therapies in inflammatory bowel disease is less well established." (PMID 38399538, 2024). "The inflammatory cytokine tumor necrosis factor alpha (TNFα) induces the assembly of the NLRP3 inflammasome, resulting in the augmented secretion of inflammatory cytokines implicated in the pathogenesis of inflammatory bowel disease (IBD)." (PMID 38667290, 2024). "Tumor necrosis factor-⍺ inhibitors are often prescribed for the treatment of inflammatory bowel disease." (PMID 38939259, 2024). "Anti-tumour necrosis factor (TNF)-α agents have been increasingly used to treat patients affected by inflammatory bowel disease and dermatological and rheumatologic inflammatory disorders." (PMID 37175894, 2023). "Anti-inflammatory drugs, such as 5-aminosalicylic acid (5-ASA) or anti-TNF-α agents, such as infliximab and adalimumab, have been used in the treatment of other inflammatory conditions, such as inflammatory bowel disease (IBD)." (PMID 37373082, 2023). "Moreover, α-MSH reduced symptoms of fecal blood and weight loss, and reduced production of TNF-α and nitric oxide in a mouse model of inflammatory bowel disease (IBD)." (PMID 36891301, 2023). "Patients with ulcerative colitis (UC), an inflammatory bowel disease (IBD) characterized by T-cell infiltration in the colon and overproduction of TNF-α and IFN-γ, also have an association with CHIP." (PMID 38162500, 2023). "In another inflammatory disease like inflammatory bowel disease curcumin have cellular targets interaction with NF‐κB, JAKs/STATs, MAPKs, TNF‐α, IL‐6, PPAR, and TRPV1." (PMID 37324924, 2023). "Approximately 5% of patients with AS or PsA with a history of HBV and inflammatory bowel disease, receiving TNF inhibitors were reported to have HBV reactivation, liver failure, or even death in severe cases." (PMID 37485474, 2023).
inflammatory bowel disease (continued). "The indication for DMARD or anti-TNF therapy in all other subjects was either spondyloarthropathy or inflammatory bowel disease control." (PMID 36038721, 2023). "Anti-tumor necrosis factor-α (TNF) therapy is a first-line biological drug for the treatment of moderate-to-severe inflammatory bowel disease, refractory to conventional therapy (mesalamine, steroids, and immunosuppressants)." (PMID 36902681, 2023). "Hepatitis B, the PI3K-Akt signalling pathway, cancer-related and proteoglycan cancer pathways, inflammatory bowel disease, Chagas disease, prostate cancer, osteoclast differentiation, colorectal cancer, and the TNF signalling pathway are the top ten pathways." (PMID 36818231, 2023). "Anti-TNF drugs such as adalimumab and infliximab have been approved for inflammatory bowel disease in clinic more than two decades." (PMID 38041080, 2023). "Blocking TNF by monoclonal antibodies was also indicated in other immune disorders such as inflammatory bowel disease (IBD) and hidradenitis suppurativa." (PMID 37569685, 2023). "Next, KEGG pathway enrichment analysis showed that these DEGs were involved in 20 pathways, including the NF-kappa B signaling pathway, TNF signaling pathway, and inflammatory bowel disease." (PMID 37299390, 2023). "which investigated the effect of soluble antigens on laminated layer of E. granulosus in inflammatory bowel disease in vivo in mice and showed that antigen B decreased the cytokines IL‐1ß, IL‐6, and TNF‐α by affecting the NF‐κB and IRAK pathways." (PMID 36582052, 2023). "Pro-inflammatory cytokines are generally upregulated in inflammatory bowel disease (IBD) including TNFα and IL-6." (PMID 38106420, 2023). "Administration of antibodies against TNF-α, IL-12/23p40, and IL-6 produced by innate immune cells is effective for treating inflammatory bowel disease (IBD)." (PMID 36845090, 2023). "Anti-tumor necrosis factor (anti-TNF) therapy has been successfully used for more than 20 years to treat inflammatory bowel diseases (IBDs), such as Crohn’s disease (CD) and ulcerative colitis (UC)." (PMID 37176606, 2023). "Support for TNFα as a therapeutic target for PD also comes from the study of inflammatory bowel disease (IBD)." (PMID 38059210, 2023). "Pro-inflammatory cytokines play an essential role in the regulation of intestinal immunity, and among them, IL-1β, TNF-α, and IL-6 abnormalities are considered to be important in the pathogenesis of inflammatory bowel disease." (PMID 38139262, 2023). "Anti-TNF antibodies have become a first-line therapy in moderate-to-severe inflammatory bowel diseases." (PMID 37200710, 2023). "Therapeutic drug monitoring (TDM) is a useful tool for optimising the use of anti-TNFα inhibitors in patients with inflammatory bowel diseases (IBDs)." (PMID 37514022, 2023). "In patients with inflammatory bowel disease, IL-24 is capable of inducing the expression of proinflammatory cytokines such as TNF-α and IL-6 as well as induction of inflammation and immune cell infiltration during tissue damage." (PMID 36806964, 2023). "The TNF-α level in the peripheral blood mononuclear cell supernatants of patients with inflammatory bowel disease (IBD) is elevated, and the presence of TRPA1 antagonists abolishes the inflammatory effects of TNF-α." (PMID 36875034, 2023). "We used the following keywords: “Inflammatory Bowel Disease”, “Crohn’s Disease”, “Ulcerative Colitis”, “cancer”, “neoplasms”, “thiopurines”, “biologic agents”, “anti-TNF”, “vedolizumab”, “ustekinumab”, “tofacitinib” and “management”." (PMID 36765829, 2023). "In this study, we investigated the potential of ASC treatment in providing an anti-inflammatory stimulus for conditions such as inflammatory bowel diseases and other sources with high levels of tumor necrosis factor (TNF)." (PMID 37851787, 2023).
inflammatory bowel disease (continued). "A recent study confirms this finding by showing that patients with inflammatory bowel disease (IBD) who were treated with anti-TNF had significantly fewer hospitalizations and deaths compared to patients treated with other anti-inflammatory medications." (PMID 37081046, 2023). "In human and animal studies, peak serum TNF-α values correlate with peak levels of injury due to intestinal ischemia and elevated TNF-α concentrations have been found in patients with Crohn’s disease and inflammatory bowel disease." (PMID 36670767, 2023). "A French population-based study found that inflammatory bowel disease (IBD) patients on TNF-alpha inhibitors had a lower rate of viral infections compared to patients on azathioprine (HR 0.57; 95% CI, 0.38–0.87)." (PMID 37304177, 2023). "Inflammatory bowel diseases (IBDs), such as Crohn’s disease or ulcerative colitis, can be treated with anti TNF-alpha (TNF-α) antibodies (Abs), but they also put patients with IBDs at risk of cancer." (PMID 37185713, 2023). "The development of the anti-tumor necrosis factor α (TNF-α) antibody infliximab defines a ground-breaking moment in the treatment of inflammatory bowel diseases (IBDs), namely Crohn’s disease (CD) and ulcerative colitis (UC)." (PMID 37443765, 2023). "Cytokines IL-1β and IL-8 were reported to be involved in the restriction of Salmonella infection, whereas TNF-α was shown to be elevated in the intestinal mucosa of inflammatory bowel disease patients, which can lead to excess inflammation and gut injury." (PMID 38247473, 2023). "Patients with inflammatory bowel disease (IBD) treated with anti-TNF therapy exhibit attenuated humoral immune responses to vaccination against SARS-CoV-2." (PMID 36634565, 2023). "CRP, TNF-α, vascular endothelial growth factor, and IL-6 participate in atherogenesis development and the pathogenesis of inflammatory bowel diseases." (PMID 36984554, 2023). "Biological agents known as anti-tumor necrosis factor (TNF) drugs are frequently utilized in the treatment of inflammatory bowel disease (IBD)." (PMID 37740137, 2023). "Recently, a study showed that the high expression of IL-1β in the intestinal mucosa was associated with resistance to corticosteroid therapy and treatment with TNFα inhibitors in inflammatory bowel diseases." (PMID 37176572, 2023). "Overexpression of TNF can lead to chronic inflammation and autoimmune diseases, such as chronic inflammatory arthritis, inflammatory bowel disease (IBD), and multiple sclerosis." (PMID 35327113, 2022). "It is known that the QFT-Plus assay results are influenced by a dysregulated immune system, such as in patients with inflammatory bowel disease on treatment with corticosteroid and/or TNF-α inhibitors and in HIV-positive patients." (PMID 35207531, 2022). "Anti-TNF alpha therapy is well-established in the treatment of juvenile idiopathic arthritis and inflammatory bowel disease." (PMID 35774100, 2022). "Infliximab and adalimumab are monoclonal antibodies against tumor necrosis factor (anti-TNF) used to manage inflammatory bowel disease (IBD)." (PMID 35631594, 2022). "Anti-tumor necrosis factor (anti-TNF) therapy has been successfully used as first-line biologic treatment for moderate-to-severe inflammatory bowel disease (IBD), in both “step-up” and “top-down” approaches, and has become a cornerstone of IBD management." (PMID 35783628, 2022). "Anti-TNF therapy is also a part of treatment regimens followed in other inflammatory disorders like psoriatic arthritis and inflammatory bowel disease (IBD), which includes Crohn’s disease (CD) and ulcerative colitis (UC)." (PMID 35788746, 2022). "Anti-tumor necrosis factor (TNF) biological therapy has generally been accepted as a standard therapeutic option in inflammatory bowel disease (IBD) patient who are refractory to steroids or immunomodulators." (PMID 35663996, 2022).
inflammatory bowel disease (continued). "TNF inhibitors are beneficial in the treatment of plaque-type psoriasis, psoriatic arthritis (PsA), RA, and inflammatory bowel disease (IBD), arousing growing interest in their use in vitiligo." (PMID 36119071, 2022). "The previous study included heterogeneous patients who received anti-TNF treatment, such as patients with RA, ankylosing spondylitis, psoriatic arthritis, and inflammatory bowel disease." (PMID 35761359, 2022). "In patients with inflammatory bowel disease (IBDs), polymorphism of NLRP12 is associated with changes in TNF-α production by peripheral blood mononuclear cells (PBMCs)." (PMID 35538558, 2022). "In 2020, the Crohn ́s & Colitis Foundation of America recommended that patients with Inflammatory Bowel Disease (IBD) that develop COVID-19 stop the anti-TNF administration (biologics or biosimilars) until they recover." (PMID 35631442, 2022). "This comparative effectiveness study, conducted among a Danish nationwide cohort, compares the effectiveness and safety of vedolizumab vs tumor necrosis factor for older patients with inflammatory bowel disease (IBD)." (PMID 36178685, 2022). "IL-7 signaling pathway influence anti-TNF responsiveness and T cell gut homing in inflammatory bowel disease." (PMID 35850640, 2022). "What is the comparative effectiveness and safety of vedolizumab vs tumor necrosis factor (TNF) antagonists for older patients with inflammatory bowel diseases (IBDs)?" (PMID 36178685, 2022). "The DEGs identified in the uninfected and DPV CHa strain-infected groups were mainly involved in cytokine-cytokine receptor interaction, Toll-like receptor signaling pathway, inflammatory bowel disease, and TNF signaling pathway." (PMID 35837399, 2022). "The onset of anemia is observed in inflammatory bowel disease, wherein TNF-α concentrations also increase; anti-TNF monoclonal antibody therapy reportedly improves the anemic state in this disease." (PMID 35371021, 2022). "Conventional drug therapies (such as thiopurines and methotrexate) are used in pediatric inflammatory bowel disease (IBD), both as primary maintenance therapy and combined with anti-tumor necrosis factor (TNF) treatment treatment to reduce the risk of developing anti-drug antibodies." (PMID 36136124, 2022). "In the KEGG enrichment analysis, DEGs were significantly enriched in cytokine–cytokine receptor interaction, IL-17 signalling pathway, TNF signalling pathway, and inflammatory bowel disease." (PMID 36386225, 2022). "Papadakis and Targan found that the serum TNF-α levels in patients with inflammatory bowel disease are elevated." (PMID 36107605, 2022). "Strikingly, targeting a single proinflammatory cytokine, tumor necrosis factor (TNF), induces both processes in a relevant cohort of inflammatory bowel disease (IBD) patients." (PMID 35383266, 2022). "The NF-κB signaling pathway has an important role in inflammatory bowel disease, which induces the secretion of inflammatory cytokines (TNF-α, IL-1β, IL-12) and upregulates the expression levels of pro-inflammatory factors COX2 and oxidative stress markers." (PMID 35450077, 2022). "Specifically, a monoclonal antibody that blocks tumor necrosis factor (TNF), infliximab, increases CRC risk in inflammatory bowel disease patients." (PMID 36499472, 2022). "We aimed to prospectively evaluate the distribution and function of T and B cells, in infants of females with inflammatory bowel disease, in utero exposed to anti-TNFα or azathioprine." (PMID 36120653, 2022). "Cytokine abnormalities, such as the elevation of IL 1, IL 6, IL 17, IL 23 and the tumor necrosis factor, are involved in HS and inflammatory bowel disease." (PMID 35203664, 2022). "The present study aimed to determine the prevalence and types of oral infections in patients with inflammatory bowel disease treated with biological therapy (anti-TNF-α and anti-integrin-α4β7) and conventional therapy." (PMID 35323234, 2022).
inflammatory bowel disease (continued). "Anti-tumour necrosis factor-alpha (anti-TNFα) therapy had been a proven strategy for treating inflammatory bowel disease, where TNFα-binding lactococci bacterium can also act as infrared fluorescent protein." (PMID 35214114, 2022). "Tumor necrosis factor-alpha (TNF-α) is an important mediator of inflammatory response with involvement in inflammatory bowel disease and CVD." (PMID 35135577, 2022). "The most popular therapies for the treatment of inflammatory bowel diseases are TNF-α monoclonal antibodies." (PMID 35585977, 2022). "The use of Tumor necrosis factor alpha (TNF-alpha) inhibitors in rheumatic and inflammatory bowel diseases has been associated with demyelinating and other inflammatory CNS conditions, including myelitis." (PMID 36247761, 2022). "KEGG signaling pathway analysis suggested that TNF regulated inflammatory response and inflammatory bowel disease." (PMID 36105284, 2022). "Similar to patients with SpA, colon IELs from the TNFΔARE/+ mouse model of inflammatory bowel disease and SpA display heightened TNF production upon stimulation." (PMID 36159826, 2022). "Corticosteroids, immunomodulators (IM) and tumour necrosis factor antagonists (anti-TNF) are commonly used in the treatment of inflammatory bowel disease (IBD) but they also supress the defence against infectious disease." (PMID 35140875, 2022). "The therapeutic efficacy of the combination in mouse cancer models demonstrated that the efficient control of inflammatory bowel disease symptoms by TNF blockers and even enhanced the tumor rejection." (PMID 36016934, 2022). "This supports the view of IL1 and IL23 as a promising target for those patients that fail to respond to TNFα inhibition, the standard of care for many severe inflammatory mediated diseases, including inflammatory bowel disease (IBD)." (PMID 35731827, 2022). "Children and adolescents with inflammatory bowel disease are often treated with immunomodulators (thiopurines, methotrexate) and biologics (anti-TNF, anti-integrin) for extended periods despite concerns about long-term safety." (PMID 37168632, 2022). "Although TNF-α inhibitors signal a new era in the treatment of inflammatory bowel disease (IBD), contributing greatly to the improvement in disease prognosis, the use of these agents is associated with a 2–8-fold increased risk of active TB." (PMID 35330505, 2022). "TDM already found its way in the field of treatment of inflammatory bowel disease with anti-TNF agents." (PMID 35683398, 2022). "In comparison to IBS patients or controls, the intensity of TNF-α was shown to be lower in Inflammatory Bowel Disease (IBD) patients." (PMID 34862947, 2022). "The use of the tumor necrosis factor-α antagonists (anti-TNFs), infliximab and adalimumab, for the management of inflammatory bowel disease (IBD) continues to be refined." (PMID 35075155, 2022). "Traditionally, TNF-α inhibitors are considered effective biological therapies for moderate-to-severe inflammatory bowel disease." (PMID 34760850, 2021). "TNF-α was also a pro-inflammatory factor, and the inhibitor of TNF-α was one of the pharmacological agents used for treating inflammatory bowel disease." (PMID 35010176, 2021). "The introduction of anti-tumor necrosis factor antibodies resulted in a considerable expansion of the options available for the treatment of inflammatory bowel disease." (PMID 33912062, 2021). "In several studies, it has been shown that inflammatory bowel disease results in increased concentrations of proinflammatory cytokines, including tumor necrosis factor alpha (TNF-α), interleukin (IL)-1β, IL-6, and IL-17." (PMID 34754319, 2021). "KEGG pathway analysis indicated RORα was involved in regulation of cytokine–cytokine receptor interactions, inflammatory bowel disease, TNF signaling pathways, and Jak-STAT signaling pathways." (PMID 33397953, 2021).